HMOX1 (heme oxygenase 1)
Diseases named in the same sentence as HMOX1 in open-access papers (continued):
Sharing a sentence is not in itself a finding about the gene and the disease.
liver failure (14 papers, 2014 to 2023). A liver disease characterized by the liver losing or has lost all of its function. "In summary, our research confirmed through animal experiments that ferroptosis-related genes Hmox1, Slc3a2, Jun and Zfp36 were significantly correlated with and highly expressed in liver failure." (PMID 35923893, 2022). "Some individuals, however, express an enzyme—heme oxygenase 1 (HO-1)—that prevents liver failure by limiting the reactive oxygen species response." (PMID 29727455, 2018). "Finally, it was confirmed by the construction of septic liver failure mice model that ferroptosis-related genes of Hmox1, Slc3a2, Jun and Zfp36 were significantly correlated with liver failure and were highly expressed." (PMID 35923893, 2022). "Seven differentially expressed ferroptosis-related genes (Hmox1, Epas1, Sirt1, Slc3a2, Jun, Plin2 and Zfp36) were obtained through the intersection of ferroptosis-related genes in the FerrDb database with DEGs in the GSE60088 dataset, and all of these genes were up-regulated in liver failure." (PMID 35923893, 2022).
lymph node metastasis (14 papers, 2014 to 2025). "Overall, these data indicate that compared with low HMOX1 expression, high HMOX1 expression is associated with increased disease stage, lymph node metastasis, and distant metastasis." (PMID 40544155, 2025). "Univariate survival analysis revealed that HMOX1 expression (p < 0.0001), clinical stage (p = 0.003), pathological grade (p = 0.047), lymph node metastasis (p < 0.0001), and distant metastasis status (p = 0.004) were prognostic indicators of overall survival." (PMID 40544155, 2025). "A higher expression of HMOX1 was correlated with more aggressive lymph node stages (N2 and N3, more than 2 lymph nodes invaded) compared to the absence of lymph node metastasis (N0) (p = 0.005)." (PMID 35053476, 2022).
Myocardial fibrosis (14 papers, 2011 to 2025). "Exercise ameliorated myocardial fibrosis in obese mice by inhibiting myocardial oxidative stress and promoting the expression of heme oxygenase 1 (HO-1)." (PMID 39796197, 2025). "Heme has been shown to be protective against myocardial fibrosis and oxidative stress through inducting of heme oxygenase 1 and the activation of the phosphatidylinositol 3-kinase/AKT signaling pathway." (PMID 36970332, 2023). "Another study demonstrated that pharmacological modulation of the heme oxygenase-1 pathway offers protection against intermittent hypoxia-induced cardiac dysfunction and myocardial fibrosis by inhibiting cell apoptosis and mitochondrial fission." (PMID 31191229, 2019).
silicosis (14 papers, 2010 to 2025). Silicosis is a respiratory disease caused by breathing in (inhaling) silica dust. "A previous study on patients with silicosis and BALB/c mice shows that increasing the content of pulmonary heme oxygenase-1 (HO-1) can inhibit the activity of reactive oxygen species (ROS) and subsequent pathologic changes, thereby attenuating progression of silicosis." (PMID 39866352, 2024).
acute liver failure (13 papers, 2016 to 2025). Rapid deterioration of liver function causing encephalopathy and coagulopathy. "In APAP-induced acute liver failure patients (GSE74000), IKBKG levels decreased, and Nrf2 target genes were also repressed (i.e., HMOX1, PRDX1, TXNRD1, GPX4, GPX1, GCLC, GCLM, and NQO1)." (PMID 38505605, 2024).
head and neck cancer (13 papers, 2004 to 2024). A primary or metastatic malignant neoplasm affecting the head and neck. "We analyzed the gene expression of HO-1 (HMOX-1) in head and neck cancer tissues from the TCGA database and found a significantly lower HMOX1 expression in tumors tissues than in normal tissues." (PMID 34503136, 2021). "The Kaplan–Meier (KM) plot revealed a longer overall survival of head and neck cancer patients with high HO-1 (HMOX1) expression than patients with low HO-1 expression (p = 0.04)." (PMID 32188144, 2020). "Herein, we also observed that head and neck cancer patients harboring high HO-1 (HMOX1) expression in tumor tissues had significantly more favorable overall survival than those with a lower level." (PMID 32188144, 2020). "Moreover, the upregulation of heme oxygenase-1 (HO-1) was found to be critical for chrysosplenol D-induced apoptotic cell death that patients with head and neck cancer had lower HO-1 expression." (PMID 34503136, 2021).
lymphosarcoma (13 papers, 2012 to 2025). "Immunohistochemical staining confirmed a compensatory increase in Hmox1 levels in the liver tissue of RLS40 lymphosarcoma-bearing mice from the control and vehicle-treated groups, which we attribute to the tumor-associated liver damage." (PMID 41465338, 2025). "In prior studies, we showed that gallium nitrate increased ROS levels in human lymphoma CCRF-CEM cells leading to an upregulation of heme oxygenase-1 (HO-1)." (PMID 32391122, 2020).
memory impairment (13 papers, 2011 to 2025). "LPS also successfully induced memory impairment in the Y maze test, neuroinflammatory responses, and oxidative stress such as increases in mRNA levels of interleukin (IL)-1β and IL-6, heme oxygenase-1, microglial activation, and iNOS activity in hippocampus." (PMID 24999480, 2014). "Additionally, GAS up-regulates the level of Nrf2 and increases the expression of downstream antioxidant stress factors, such as heme oxygenase 1 (HO-1) and GPx4.Our study also confirmed the effect of GAS on learning and memory impairment." (PMID 36234847, 2022).
allergic asthma (12 papers, 2011 to 2024). A asthma with a basis in a pathological type I hypersensitivity reaction. "In addition, we investigated the modulation of mitogen-activated protein kinase (MAPK)/NF-E2-related factor 2 (Nrf2)/heme oxygenase-1 (HO-1) and nuclear factor-κB (NF-κB) activations to identify the mechanism underlying the anti-oxidant and anti-inflammatory effects of AE allergic asthma." (PMID 31611811, 2019).
cognitive decline (12 papers, 2016 to 2025). "Overexpression of Hmox1 causes cognitive decline by regulating tauopathy in mice." (PMID 32992485, 2020). "In the amyloid precursor protein/presenilin 1 (APP/PS1) transgenic mice, puerarin increased NrF‐2 and its downstream antioxidant molecule heme oxygenase 1 (HO‐1) and alleviated oxidative stress damage, blocked amyloid beta (aβ) deposition, and rescued cognitive decline." (PMID 34964013, 2021). "We detected less DNA methylation of the HMOX1 gene in the blood of AD patients compared with MCI patients and control individuals, and reduced levels of DNA methylation of the HMOX1 gene at the −374 CpG site were closely associated with cognitive decline in AD patients." (PMID 27058954, 2016).
influenza (12 papers, 2010 to 2025). An acute viral infection of the respiratory tract, occurring in isolated cases, in epidemics, or in pandemics; it is caused by serologically different strains of viruses (influenzaviruses) designated A, B, and C, has a 3-day incubation period, and usually lasts for 3 to 10 days. "In response, enzymatic defenses including heme oxygenase 1 (Hmox1), Gpx1, and thioredoxin reductase 1 can be induced during influenza infection." (PMID 22355371, 2012). "Finally, consistent with the presence of influenza-induced inflammation, the levels of Hmox1 (abundant in LPS-activated macrophage) also increased with a peak at 13 dpi, that is consistent with the observed increase in transcript levels." (PMID 22355371, 2012).
kidney (12 papers, 2019 to 2026). "Background and aims: Diabetic kidney is more sensitive to ischemia/reperfusion (I/R) injury, which is associated with increased oxidative stress and impaired nuclear factor erythroid 2-related factor 2 (Nrf2)/heme oxygenase-1 (HO-1) signaling." (PMID 30578379, 2019). "Recent studies have shown that the Nrf2/antioxidant−responsive element (ARE)/heme oxygenase 1 (HO−1) pathway is a potential target for kidney protection in various drug−induced kidney injury models." (PMID 37685936, 2023). "Furthermore, MAT2A was reported to act as a transcriptional corepressor for heme oxygenase-1 (HO-1) expression by supplying SAM for methyltransferases, thus it was suggested to act as a tumor suppressor in kidney carcinogenesis." (PMID 34065390, 2021).
Shock (12 papers, 2008 to 2025). The state in which profound and widespread reduction of effective tissue perfusion leads first to reversible, and then if prolonged, to irreversible cellular injury. "Both, reducing local inflammation and upregulating cell adherence proteins could enhance the reliance of intestinal tissue against hemorrhagic shock and hypoxic tissue damage without an activation of heme oxygenase-1." (PMID 41233883, 2025).
squamous cell carcinoma (12 papers, 2011 to 2023). A carcinoma arising from squamous epithelial cells. "In the previous studies it was found that blue light treatment induced upregulation of Nrf2 in A431 epidermoid carcinoma cells and resulted in significantly increased levels of heme oxygenase 1 (HO-1), an anti-inflammatory and antioxidative factor." (PMID 34357042, 2021).
abdominal aortic aneurysm (11 papers, 2016 to 2024). Enlargement and ballooning of the vessel that supplies arterial blood to the abdomen, pelvis and legs. "However, in line with our current findings, a recent study demonstrated that induction of HMOX1 is linked to the severity of disease in human abdominal aortic aneurysms." (PMID 39695164, 2024). "Recently, some studies have suggested the protective function of heme oxygenase-1 (HO-1) in the abdominal aortic aneurysm (AAA)." (PMID 34572356, 2021).
Cirrhosis (11 papers, 2011 to 2025). A chronic disorder of the liver in which liver tissue becomes scarred and is partially replaced by regenerative nodules and fibrotic tissue resulting in loss of liver function. "Finally, up-regulation of alpha-actinin-1, Band 4.1-like protein 2 (EPB41L2), asparagine synthetase (ASNS), and down-regulation of heme oxygenase (HMOX1) are correlated with cirrhosis." (PMID 36016316, 2022).
diabetic neuropathy (11 papers, 2016 to 2025). A chronic, pathological complication associated with diabetes mellitus, where nerve damages are incurred due to diabetic microvascular injury involving small blood vessels that supply these nerves, resulting in peripheral and/or autonomic nerve dysfunction. "Rutin administered to mice reduced oxidative stress to mitigate diabetic neuropathy by means of HMOX1 and NFE2L2." (PMID 40429928, 2025).
endometriosis (11 papers, 2021 to 2025). The growth of functional endometrial tissue in anatomic sites outside the uterine body. "It is reported that HMOX1 is highly expressed in endometriosis and gene analysis confirms that HMOX1 gene polymorphism is associated with endometriosis." (PMID 38012607, 2023). "Compared to normal endometrium, endometriosis samples showed elevated levels of heme-degradation-pathway-associated genes: Hmox1 (encoding HO-1), BLVR-A and BLVR-B, and hemopexin (Hx) as well as haptoglobin (Hp), a hemoglobin scavenger." (PMID 35565370, 2022). "In summary, our present results show that endometriosis is associated with functional polymorphism of HMOX1 gene promoter." (PMID 33800989, 2021). "It would be of interest to correlate HMOX1 polymorphism with some clinical features of endometriosis such as stage of the disease, lesion type and their location." (PMID 33800989, 2021). "The results of our study show that endometriosis is related to functional polymorphism in the promoter of HMOX1 gene." (PMID 33800989, 2021). "Haem oxygenase 1 (HMOX-1), an enzyme responsible for the catabolism of haemoglobin and known to be protective against inflammation and oxidative stress, was also found to have a functional polymorphism in women with endometriosis." (PMID 37638130, 2023). "Therefore, the aim of the study was to reveal a possible association of endometriosis with a stress-inducible heme oxygenase 1 (HMOX1)." (PMID 33800989, 2021). "Clinical significance of HMOX1 promoter polymorphism in endometriosis also remains obscure." (PMID 33800989, 2021). "For this purpose, 228 patients with clinically confirmed endometriosis and 415 control parous women from general Polish population were examined for functional –413A>T (rs2071746) single-nucleotide polymorphism (SNP) and (GT)n dinucleotide repeat length polymorphism in the promoter of HMOX1 gene." (PMID 33800989, 2021). "Therefore, the aim of the present study was to assess whether endometriosis is associated with known functional polymorphisms of HMOX1 gene." (PMID 33800989, 2021). "In endometriosis, HO-1 is up-regulated and the functional polymorphism of HMOX1 is associated with endometriosis." (PMID 38549776, 2024). "In a mouse model of endometriosis, which is characterized by chronic sterile inflammation and oxidative stress, levels of HMOX1 in peritoneal macrophages were upregulated and correlated with an increase iron content in endometriosis tissue." (PMID 38585264, 2024). "HMOX1 dysregulation has been implicated in PCOS, endometriosis, and in-vitro is down-regulated in endometrial stromal fibroblasts obtained from healthy patients in late secretory phase." (PMID 38745948, 2024). "HMOX1 suppresses ferroptosis and is upregulated in endometriosis providing a novel mechanism for treatment." (PMID 37638130, 2023). "Determing the pathway of HMOX1 involved in embryo ferroptosis in endometriosis requires further investigation." (PMID 34782602, 2021). "More work is needed to understand the role of HMOX1 to facilitate the identification of optimal targets for future endometriosis infertility treatment efforts." (PMID 34782602, 2021). "It should be stressed, however, that final elucidation of the regulatory mechanism(s) of HMOX1 expression in endometriosis requires more extensive studies." (PMID 33800989, 2021). "Moreover, two differentially expressed proteins (Heme oxygenase 1 and Acyl-CoA 6-desaturase) were verified and they can be potential biomarkers for endometriosis treatment." (PMID 38012607, 2023). "Expression of HMOX1 may be stimulated by inflammatory cytokines as well as oxidative stress agents which are known to be involved in the pathogenesis of endometriosis." (PMID 33800989, 2021). "The specific role of HMOX1 in etiopathogenesis of endometriosis also remains to be established." (PMID 33800989, 2021).
endometriosis (continued). "FADS-2, a member of fatty acid desaturase, is rarely studied in endometriosis, but both FADS-2 and HMOX1 are involved in ferroptosis, a new programmed cell death characterized by the accumulation of lipid reactive oxygen species (ROS) and dependence of iron." (PMID 38012607, 2023). "We identified HMOX1 and FADS-2 as potential endometriosis molecular treatment targets in the future." (PMID 38012607, 2023).
iron deficiency (11 papers, 2013 to 2026). "Zinc protoporphyrin IX (ZnPP), a naturally occurring molecule formed in iron deficiency or lead poisoning, is a potent competitive inhibitor of heme oxygenase-1 (HO-1)." (PMID 23476651, 2013). "Current knowledge proposes iron deficiency or hypoxia to act via nuclear HIF-1/FIF-2a/HIF-b, triggering a transcriptional induction of Tfrc together with Hmox1, Slc11a2 (DMT1), Slc40a1 (FPN1), Epo, and Cp." (PMID 33023155, 2020). "Although Hmox1 was not upregulated, several heme-scavenging genes (Hpx, Lrp1/Cd91) were induced, while others involved in heme or biliverdin handling (Slc48a1/Hrg1, Pgrmc1, Blvrb) were downregulated, suggesting a compensatory shift in heme-related processes consistent with iron deficiency." (PMID 41598416, 2026).
pulmonary TB (11 papers, 2013 to 2024). "For example, HMOX1 downregulated the expression and secretion of MMP-1 in chondrocytes or plasma of patients with pulmonary tuberculosis." (PMID 27829220, 2016).
ulcer (11 papers, 2015 to 2025). "It was reported that heme oxygenase-1 (HO-1) retains defensive qualities against ethyl alcohol-induced ulcers via the Nrf2/HO-1 pathway." (PMID 36432009, 2022). "Ulcer score, gastric acidity, gastric contents of malondialdehyde (MDA), nitric oxide (NO), heme oxygenase-1 (HO-1), and carboxyhemoglobin (COHb) blood content were estimated." (PMID 36882659, 2023).
Ureteral obstruction (11 papers, 2010 to 2025). Obstruction of the flow of urine through the ureter. "Furthermore, heme oxygenase-1 (HO-1) expression, a sensitive indicator of cellular oxidative stress, was also found to be induced as early as 12 hours after ureteral obstruction." (PMID 20412564, 2010).
age-related macular degeneration (10 papers, 2012 to 2025). Age-related loss of vision in the central portion of the retina (macula), secondary to retinal degeneration. "Clinical transcriptome data were used to evaluate HMOX1 expression in patients with age-related macular degeneration (AMD)." (PMID 36362853, 2022). "Finally, the correlation between the expression of HMOX1 and its coactivator MLL1 in patients with age-related macular degeneration (AMD) was investigated, suggesting the possibility of future clinical applications." (PMID 36362853, 2022).
cardiac arrest (10 papers, 2018 to 2025). Cessation of breathing and/or cardiac function. "Under high glucose conditions, it has been found that heme-oxygenase-1 (HO-1) overexpression via human HO-1 recombinant plasmid inhibited dysfunction of cardiac arrest, improving autophagy levels." (PMID 33228222, 2020).
experimental autoimmune encephalomyelitis (10 papers, 2009 to 2025). An autoimmune demyelinating disease of the central nervous system that is produced experimentally in animals by the injection of homogenized brain or spinal cord in Freund's adjuvant. "Heme-oxygenases(HMOX) are an important defensive mechanism against oxidative stress, and HMOX1 is overexpressed in the brain and spinal cord of MS patients and in experimental autoimmune encephalomyelitis(EAE)." (PMID 26868429, 2016). "Ectopic expression studies reveal that even small changes in expression of IDO, HMOX-1, or mitochondrial superoxide dismutase (SOD2) can prevent demyelination in experimental autoimmune encephalomyelitis (EAE) animal models of MS." (PMID 19461950, 2009).
interstitial lung disease (10 papers, 2018 to 2025). A diverse group of lung diseases that affect the lung parenchyma. "Here, we describe a phenotype expansion for HMOX1-deficiency to include not only asplenia and hepatomegaly, but also interstitial lung disease with cholesterol granulomas and inflammatory flares with hemophagocytosis present in the bone marrow." (PMID 33066778, 2020).
mastitis (10 papers, 2016 to 2025). Inflammation of breast tissue during lactation or postpartum due to an obstructed duct or infection. "Transcriptomic profiling of S. aureus-challenged Mac-T cells showed a progressive increase in DEGs as bacterial strains from low to high SCC and clinical mastitis stimulated the cells, with ferroptosis-related genes (HMOX1, SAT1) consistently upregulated across all stages." (PMID 40141146, 2025). "Key ferroptosis regulators, such as SAT1 and HMOX1, are proposed as stable molecular markers of mastitis susceptibility, regardless of strain variation." (PMID 40141146, 2025). "Notably, the expression levels of HMOX1 and SAT1 were significantly increased in S. aureus-challenged Mac-T cells, and this upregulation was consistent with trends observed in transcriptome data from mother–daughter pairs of cows with subclinical mastitis caused by S. aureus infection." (PMID 40141146, 2025). "Furthermore, the analysis of transcriptomic data from mother–daughter pairs affected by subclinical mastitis demonstrated elevated expression of both SAT1 and HMOX1 in the infected groups compared to the healthy controls." (PMID 40141146, 2025).